TNR (tenascin R)
Description:
Neural extracellular matrix (ECM) protein involved in interactions with different cells and matrix components. These interactions can influence cellular behavior by either evoking a stable adhesion and differentiation, or repulsion and inhibition of neurite growth. Binding to cell surface gangliosides inhibits RGD-dependent integrin-mediated cell adhesion and results in an inhibition of PTK2/FAK1 (FAK) phosphorylation and cell detachment. Binding to membrane surface sulfatides results in a oligodendrocyte adhesion and differentiation. Interaction with CNTN1 induces a repulsion of neurons and an inhibition of neurite outgrowth. Interacts with SCN2B may play a crucial role in clustering and regulation of activity of sodium channels at nodes of Ranvier. TNR-linked chondroitin sulfate glycosaminoglycans are involved in the interaction with FN1 and mediate inhibition of cell adhesion and neurite outgrowth. The highly regulated addition of sulfated carbohydrate structure may modulate the adhesive properties of TNR over the course of development and during synapse maintenance (By similarity).
Synonyms: TN-R; NEDSTO
Tractability: Antibody: its Gene Ontology location is reachable by antibodies, with high confidence; UniProt places it where antibodies can reach, with medium confidence; UniProt predicts a signal peptide or a membrane-spanning region. PROTAC: its protein half-life has been measured.
Gene: Protein-coding gene on chromosome 1 (175,315,194 to 175,743,595, reverse strand). Ensembl gene ENSG00000116147.
Subcellular location: Secreted, extracellular space, extracellular matrix
Pathways (Reactome):
Extracellular matrix organization: ECM proteoglycans
Gene Ontology:
Biological process: axon guidance; cell adhesion; nervous system development; modulation of chemical synaptic transmission; regulation of cell adhesion; regulation of cell differentiation; regulation of cell migration
Cellular component: extracellular matrix; extracellular region; tenascin complex; cell surface; glutamatergic synapse; membrane raft; perineuronal net; Schaffer collateral - CA1 synapse
Genetic constraint (gnomAD): Loss-of-function variants: 43 observed, 148.61 expected, observed/expected ratio (o/e) 0.29, 90% interval 0.23 to 0.37. The upper end of that interval is the gene's LOEUF score, 0.37, which puts it in group 1 of 6, group 1 being the genes least tolerant of losing a copy. Missense variants: 1,491 observed, 1,768.3 expected, observed/expected ratio (o/e) 0.84, 90% interval 0.81 to 0.88. Synonymous variants: 656 observed, 685.31 expected, observed/expected ratio (o/e) 0.96, 90% interval 0.9 to 1.02.
Gene-disease validity (ClinGen):
ClinGen rates the evidence that TNR causes each of these diseases.
neurodevelopmental disorder, nonprogressive, with spasticity and transient opisthotonus (autosomal recessive): Definitive.
Homologues: Orthologues: chimpanzee TNR (99% identical), macaque TNR (98% identical), pig TNR (94% identical), guinea pig TNR (94% identical), rat Tnr (94% identical), mouse Tnr (93% identical), rabbit TNR (93% identical), dog TNR (93% identical), tropical clawed frog tnr (62% identical), zebrafish tnr (61% identical). Paralogues in human: TNC (46% identical), TNXB (34% identical), TNN (31% identical), FN1 (22% identical), FCN1 (10% identical), FCN2 (10% identical), ANGPT1 (10% identical), ANGPTL2 (10% identical), FIBCD1 (10% identical), ANGPT2 (10% identical), FCN3 (9% identical), FGL2 (9% identical), and 13 more.
Diseases named in the same sentence as TNR in open-access papers:
TNR is named in the same sentence as 52 diseases in open-access papers, as found by Europe PMC text mining. Sharing a sentence is not in itself a finding about the gene and the disease. The quoted sentences say what the papers report.
glioma (9 papers, 2014 to 2025). A benign or malignant brain and spinal cord tumor that arises from glial cells (astrocytes, oligodendrocytes, ependymal cells). "It has been suggested that Tenascin-R (TN-R) and Tenascin-W (TN-W), as members of the tenascin family, may be associated with progression and malignancy of glioma cells; however, that hypothesis remains to be elucidated." (PMID 34149360, 2021). "This analysis identified CSPG4, PTPRZ1, and BCAN as the most highly expressed and concordant ECM targets in adult gliomas, while GPC1, CSPG5, and TNR were the top concordant targets in pediatric gliomas." (PMID 40517137, 2025). "Among the proteins specific for the cystic fluid of CG that are known to play an important role in gliomas, there were tenascin-R (TNR), histones H2A (H2A2A) and H2B (H2B)." (PMID 37627098, 2023). "In contrast, TNR is highly expressed in normal oligodendrocytes, neurons, and non-invasive gliomas such as pilocytic astrocytic tumors, but its expression decreases in malignant astrocytoma." (PMID 32906679, 2020). "According to a proteomics study of gliomas, TNR is down-regulated in glioblastomas." (PMID 32848578, 2020). "Contactin-1, tenascin-C and tenascin-R have adhesion and migration effects in glioma cells." (PMID 25238264, 2014). "The collagen and glycoprotein profiles in pediatric HGGs showed partial overlap with adult tumors, with three of the top glycoproteins in adult gliomas (VTN, TNR, and PLG) also among the most highly expressed proteins in pediatric gliomas." (PMID 40517137, 2025). "Brevican (BCAN) which is known to bind to tenascin-R (TNR) with high affinity, is highly expressed in gliomas, initiating cells’ extracellular niche in human GBM tumors and is expressed by glioma initiating cells in vitro." (PMID 30626092, 2019).
Anxiety (4 papers, 2015 to 2025). Intense feelings of nervousness, tension, or panic often arise in response to interpersonal stresses. "CMYA5, MCTP1, RXRG, and TNR are associated with mouse anxiety and human BD." (PMID 26190982, 2015). "We identify four genes (TNR, RXRG, MCTP1, and CMYA5) associated with anxiety in mice and risk of BD in humans." (PMID 26190982, 2015). "Tenascin-R knockout mice display an impairment of motor coordination and increased anxiety levels, while brevican knockout mice did not exhibit deficits in learning and memory." (PMID 35714111, 2022).
dementia (3 papers, 2022 to 2024). Loss of intellectual abilities interfering with an individual's social and occupational functions. "Comparing the average of SHAP values for core proteins for all dementia subtypes, TNR showed the highest, followed by THY1 and SMPD1, and only these three proteins presented positive values due to the low proportion of AD and VD participants in the validation cohort." (PMID 39226887, 2024). "In the search for more ECM-encoding RNAs in the database we also detected the brevican interaction partner tenascin-R (TNR), which showed group-wise down-regulation in hippocampus, temporal cortex and frontal white matter of dementia samples." (PMID 36982604, 2023).
schizophrenia (3 papers, 2018 to 2023). A major psychotic disorder characterized by abnormalities in the perception or expression of reality. "Some of the candidate genes are also known to play a role in neuronal diseases like Alzheimer’s disease (EIF4B), schizophrenia (CACNG8) or Parkinson’s disease (TNR)." (PMID 36624125, 2023).
attention deficit-hyperactivity disorder (2 papers, 2021). A disorder characterized by a marked pattern of inattention and/or hyperactivity-impulsivity that is inconsistent with developmental level and clearly interferes with functioning in at least two settings (e.g. at home and at school). "It has been implicated that TNR was known to function in many neurological diseases, such as attention deficit hyperactivity disorder (ADHD) and neurodegenerative disorders." (PMID 33407712, 2021). "Mutations found in the TN-R encoding gene (TNR) are associated with predisposition for neurodevelopmental pathologies, such as attention deficit hyperactivity disorder and non-progressive form of spastic disorders." (PMID 34054795, 2021).
bipolar depression (2 papers, 2015 to 2025). "Overall, our study provides evidence for the association of CMYA5, MCTP1, RXRG, and TNR with bipolar disorder." (PMID 26190982, 2015). "Hyperglycosylation of another extracellular matrix protein tenascin-R, was observed in both unipolar and bipolar depression." (PMID 40671800, 2025). "We find that the calcium signaling pathway is enriched in genes commonly coexpressed with RXRG and TNR, and disruptions in calcium signaling are part of the pathophysiology of bipolar disorder." (PMID 26190982, 2015). "We then investigate the homologous genomic regions in human bipolar disorder GWAS data and thus identify four candidate genes (TNR, RXRG, MCTP1, and CMYA5)." (PMID 26190982, 2015).
glioblastoma (2 papers, 2019 to 2020). The most malignant astrocytic tumor (WHO grade IV). "A strong TNR expression is linked to non-invasive brain tumor (pilocytic astrocytomas) whereas a weak expression is detected in glioblastoma." (PMID 30626092, 2019). "The exact role of TNR, particularly in glioblastoma stem cells extracellular niche, is a subject worth exploring." (PMID 30626092, 2019).
lung carcinoma (2 papers, 2016 to 2024). "After correcting for multiple testing (0.05/533 exGS tests), we identified 28 associations, including 24 for NHL, 2 for leukaemia (SRP14, TREML2), 1 for both liver (KRT18) and lung cancer (TNR)." (PMID 38750076, 2024).
retinal ischemia (2 papers, 2017 to 2024). A ischemic disease that involves the retina. "Nevertheless, based on the enhanced staining of tenascin-R upon retinal ischemia, horizontal cells seem to react to retinal damage." (PMID 28262779, 2017). "Also, the extracellular protein Tenascin-R has been reported to increase in the OPL in a mouse model of retinal ischemia." (PMID 39348530, 2024).
alcohol dependence (1 paper, 2013). Physical and psychological dependence on alcohol. "The KIAA0040 gene is flanked by two genes TNN and TNR with a plausible role in alcohol dependence." (PMID 24829844, 2013).
complement deficiency (1 paper, 2025). A genetic deficiency of any of the component of the complement system (including the classical, alternative, and terminal pathway components), that can either be acquired or inherited. "The lung cross-species signature includes multiple carcinoma-associated genes (TNR, SCD) and, to a lesser extent, genes involved in complement deficiency (CFD, C3) and NAD+ metabolism (NNMT), all of which may be considered aging-associated processes." (PMID 40249926, 2025).
COVID-19 (1 paper, 2022). A disease caused by infection with severe acute respiratory syndrome coronavirus 2. "Although another proinflammatory member of this family (i.e., Tenascin C) has been identified in the exosomes of COVID-19 patients, no data on Tenascin R could be found in COVID-19-related literature." (PMID 36012423, 2022).
Ehlers-Danlos syndrome type III (1 paper, 2014). "One of these, TNR coding for tenascin R, is a candidate gene for PL, because mutations in one of its paralogues, TNXB, are known to cause Ehlers-Danlos syndrome type III in humans (omim:130020)." (PMID 24886090, 2014).
epilepsy (1 paper, 2016). A brain disorder characterized by episodes of abnormally increased neuronal discharge resulting in transient episodes of sensory or motor neurological dysfunction, or psychic dysfunction. "The deficits of PNNs measured by reduced WFA numbers and decreased tenascin-R, aggrecan and neurocan protein levels might be related to the pathophysiology of epilepsy induced by PTZ." (PMID 27880801, 2016).
glaucoma (1 paper, 2021). Increased pressure in the eyeball due to obstruction of the outflow of aqueous humor. "Based on the unaltered tenascin-R levels upon IOP-elevation, tenascin-R expressing cells in our glaucoma model do not seem to respond to damage." (PMID 33668263, 2021).
invasive breast carcinoma (1 paper, 2020). A carcinoma that infiltrates the breast parenchyma. "As a next step we compared the expression levels of tenascin genes (TNC, TNN, TNR, TNXB) in invasive breast cancer using GEPIA program." (PMID 32817625, 2020).
mental disorder (1 paper, 2015). A disease that has its basis in the disruption of mental process. "The large number of commonly coexpressed genes between RXRG and TNR, and the enrichment of these genes in mental disorder related annotations, strongly suggests that they are part of the same mental disorder related network." (PMID 26190982, 2015). "This suggests that although genes related to, for example, mental disorders are enriched in the overlap between TNR and RXRG, and in the overlap between MCTP1 and RXRG, they are not the same genes, i.e., both sets of genes are independently related to mental disorders." (PMID 26190982, 2015). "A systems genetics approach suggests that TNR, RXRG, and MCTP1 coexpress with several other genes related to mental disorders in the striatum, providing a potential mechanism of action." (PMID 26190982, 2015).
ovarian carcinoma (1 paper, 2013). A malignant neoplasm originating from the surface ovarian epithelium. "Epidemiological studies also suggest a correlation between CAG repeat deletions in the androgen receptor and prostate and ovarian cancers, implying that TNR deletions are equally as important as TNR expansions in causing human diseases." (PMID 23468897, 2013).
Seizure (1 paper, 2019). A seizure is an intermittent abnormality of nervous system physiology characterized by a transient occurrence of signs and/or symptoms due to abnormal excessive or synchronous neuronal activity in the brain. "Seizure upregulates the expression of multiple ECM molecules, including tenascin-C, tenascin-R, neuronal pentraxin 2, and hyaluronan." (PMID 31827499, 2019).
status epilepticus (1 paper, 2016). Status epilepticus is defined as a continuous seizure lasting more than 30 min, or two or more seizures without full recovery of consciousness between any of them. "It has been demonstrated that tenascin-R is associated with an episode of pilocarpine-induced status epilepticus through modulation of mossy fiber sprouting and astrogliosis." (PMID 27880801, 2016).
uterine carcinoma (1 paper, 2014). A carcinoma involving a uterus. "We found that the tenascin R gene was expressed only in stage III human uterine carcinomas, which may be an important sign for acquiring an invasive cancer phenotype." (PMID 25231141, 2014).
tumor (8 papers, 2015 to 2025). "The genes TNR, OLIG1, and PDGFRA are specific to the OPC cluster and are differentially expressed in tumor and periphery cells." (PMID 35327982, 2022).
cancer (7 papers, 2014 to 2025). A tumor composed of atypical neoplastic, often pleomorphic cells that invade other tissues. "Inhibiting properties of Tenascin-R were described in regard to adhesion of mesenchymal and neural cells on Fibronectin, whereas the role of Tenascin-R has barely been investigated in cancer." (PMID 32560557, 2020). "LAMA1, CHAD, ITGA8, and COL11A1 consistently showed hypermethylation in more than half of cancer types; on the contrary, TNN, SPP1, COL6A6, and TNR consistently showed hypomethylation in more than half of types of cancer." (PMID 36311789, 2022).
psychiatric disorder (3 papers, 2015 to 2023). A disorder characterized by behavioral and/or psychological abnormalities, often accompanied by physical symptoms. "TNR is known to function in biological processes such as neural cell adhesion, neurite outgrowth and modulation of sodium channel function that have been implicated in the aetiology of psychiatric disorders." (PMID 30563984, 2018).
neurodevelopmental disorder (1 paper, 2021). A behavioral and cognitive disorder with onset during the developmental period that involves impaired or aberrant development of intellectual, motor, or social functions. "In another study, researchers found that TNR deficiency would cause an early onset and nonprogressive neurodevelopmental disorder." (PMID 33407712, 2021).
TNR also shares sentences with these, for which no sentence is quoted: cognitive deficits (4 papers); Intellectual disability (3); Alzheimer disease (2); neurological diseases (2); brain disorder (1); brain tumor (1); cardiovascular disease (1); cognitive decline (1); connective tissue disorder (1); demyelination (1); diabetes (1); Down syndrome (1); Ehlers-Danlos syndrome (1); experimental autoimmune encephalomyelitis (1); familial Alzheimer disease (1); ischemia (1); leukaemia (1); malignant astrocytoma (1); malignant brain tumor (1); medulloblastoma (1); metastatic tumors (1); narcolepsy (1); Parkinson disease (1); peritonitis (1); pilocytic astrocytoma (1); pulmonary embolism (1); Stroke (1).